CLDN4 (claudin 4)
Diseases named in the same sentence as CLDN4 in open-access papers (continued):
Sharing a sentence is not in itself a finding about the gene and the disease.
ovarian carcinoma (continued). "Eight genes were overexpressed in ovarian cancer samples compared with normal tissue samples and included CLDN1, CLDN3, CLDN4, CLDN6, CLDN7, CLDN9, CLDN10, and CLDN16." (PMID 34249076, 2021). "Among them, CLDN3, CLDN4, CLDN6, CLDN10, CLDN15, and CLDN16 were significantly correlated with overall survival in patients with ovarian cancer." (PMID 34249076, 2021). "EpCAM, claudin-4 and −7, and CD82 coexpression correlated with the metastasis and drug resistance in ovarian cancer." (PMID 32091301, 2020). "Consistent with our data, CLDN3, CLDN4, and CLDN7 have been shown to suppress EMT in ovarian carcinoma cells and lung cancer cells." (PMID 28867761, 2017). "A recent study reported the overexpression of CLDN4 in platinum-resistant EOC patients compared to platinum-sensitive ones and demonstrated an increased sensitivity of ovarian cancer cells to cisplatin after in vitro suppression of CLDN4 expression by siRNA." (PMID 28545541, 2017). "We examined claudin-4 activity in human ovarian tumor cell lines (SKOV3, OVCAR3, PEO4) using in vitro caspase and scratch assays as well as an in vivo mouse model of ovarian cancer." (PMID 27724921, 2016). "As ovarian carcinoma is largely a disease of the peritoneal cavity, the utilization of intra-peritoneal (i.p) treatment with full length CPE holds promise for this claudin-4 expressing tumor." (PMID 23685873, 2013). "CTR1 gene expression was reduced in CLDN3 or CLDN4 knockdown cells, and enforced CTR1 expression restored their sensitivity to cisplatin, indicating that CTR1 plays a role in cisplatin sensitivity in ovarian cancer cells." (PMID 24009024, 2013). "Recent work shows that, in addition to the CLDN3 and CLDN4 genes, CLDN7 is frequently elevated in ovarian cancer." (PMID 21789222, 2011). "Previous studies have shown that claudin-7 is frequently upregulated in epithelial ovarian cancer (EOC) along with claudin-3 and claudin-4." (PMID 21789222, 2011). "Our results established, to our knowledge for the first time, that the CPE peptide is capable of specifically targeting chemotherapy resistant ovarian carcinoma cells overexpressing the CPE receptors claudin-3 and claudin-4." (PMID 20598131, 2010). "In ovarian cancer, for example, where both CLDN3 and CLDN4 are highly up regulated and where intraperitoneal therapy is possible, CPE treatment is certainly an interesting possibility." (PMID 16836752, 2006). "Two humanized antibodies targeting the ECL2 of CLDN4 (KM3934 and xi-5D12), demonstrated ADCC when co-cultured with human Peripheral Blood Mononuclear Cells (PBMCs) and ovarian cancer cells (KM3934) or human and mouse CLDN4 expressing cells (xi-5D12), respectively." (PMID 38371623, 2024). "The inhibition of claudin-4 may affect DNA damage repair in cancer cells and enhance the effectiveness of PARP inhibitors in ovarian cancer." (PMID 39458944, 2024). "Subsequently, the survival and immune infiltration analysis demonstrated that the upregulation of five candidate genes, ITGB2, VEGFA, CLDN4, OCLN, and SPP1, were correlated with an unfavorable clinical outcome and increased immune cell infiltration in ovarian cancer." (PMID 36980477, 2023). "CLDN4 knockdown increased cellular accumulation and sensitivity to cisplatin, pointing towards the potential involvement of CLDN4 in platinum resistance in ovarian cancer, in line with the enhanced sensitivity toward carboplatin and paclitaxel upon CLDN1 knockdown in ovarian cancer cells." (PMID 36672179, 2023). "However, CLDN3, CLDN4 40, and CLDN7 41 have been shown to suppress EMT in ovarian carcinoma cells and lung cancer cells." (PMID 34405008, 2021). "However, claudin-1, claudin-4, and claudin-10 have been shown to be differentially expressed during the EMT in oral lichen planus and ovarian carcinomas." (PMID 33193109, 2020). "It is interesting to consider that claudin-4 and CA125 could be tested in combinations for their possible use as prognostic biomarkers in ovarian cancers." (PMID 30322133, 2018).
ovarian carcinoma (continued). "In attempts to create spheroids from the MDR ovarian cancer cell line, A2780ADR, we observed a lack of tight association of the cells that was likely due to low expression of claudin 4 which is required for spheroid formation." (PMID 29343829, 2018). "CLDN3 and CLDN4, which are Clostridium perfringens enterotoxin (CPE) receptors, affected chemoresistance mediated by CPE in ovarian cancers, it was also reported that CLDN3 and CLDN4 modulated the sensitivity to cisplatin partially through the copper and cisplatin influx transporter CTR1." (PMID 29116019, 2017). "Normal ovarian surface epithelial cells do not express either claudin-3 or claudin-4, however these claudins are both expressed at high levels in the majority of ovarian cancers." (PMID 23685873, 2013). "While normal ovarian surface cells do not express CLDN3 and CLDN4 these two proteins are up-regulated and expressed at high levels in as many as 92% of ovarian cancers presumably as a result of the MET." (PMID 23805314, 2013). "Claudin-3 and claudin-4 overexpression in this study was determined by their non-detectable expression in normal ovarian surface epithelium based on the notion that ovarian cancer originates in the normal ovarian surface epithelium." (PMID 24009024, 2013). "The 2008 ovarian cancer cell line expresses both CLDN3 and CLDN4, and we have previously reported on the subline 2008-CLDN3KD-4.5, in which the expression of CLDN3 was knocked down using a lentiviral vector expressing a short hairpin RNA targeted to CLDN3 mRNA." (PMID 21303546, 2011). "Because claudin-3 and claudin-4 have been recognized as the receptors for Clostridium perfringens enterotoxin (CPE), these findings imply that ovarian cancer refractory to standard treatment modalities may be susceptible to CPE-based therapeutic approaches." (PMID 20598131, 2010). "Claudin-3 was therefore considered less likely than claudin-4 to represent a useful plasma-based ovarian cancer biomarker and was not studied further." (PMID 19619303, 2009). "Significantly, unlike CA125, claudin-4 and claudin-3 have been shown elevated in all subtypes of ovarian cancer." (PMID 19619303, 2009). "It was found that the methyl-CpG-binding domain protein 2 (MBD2) was recruited to CpG sites and silenced the CLDN4 gene in ovarian cancer cell lines without interfering with SP1 binding." (PMID 18423053, 2008). "We found that claudin-4 forms an axis with the amino acid transporters SLC1A5 and LAT1 to regulate autophagy, facilitating the elimination of a product of genome instability, micronuclei, thus preventing the accumulation of genomic instability in ovarian cancer." (PMID 38867360, 2024). "However, the associations are not always linear, like in case of claudin-3 or claudin-4 in ovarian cancer, where its expression is increasing during metastases." (PMID 32197343, 2020). "Phosphorylation is shown to be having a regulatory role in the function of claudin-3 and claudin-4, for example, activated PKA or PKC phosphorylates claudin-3 and claudin-4 and enhance the paracellular permeability in ovarian cancer cells through the mislocalization of claudins." (PMID 30728783, 2018). "In ovarian cancer cells, phorbol ester-mediated PKC activation induced phosphorylation of claudins and decreased barrier function, and in human epidermal keratinocytes, formation of TJs was suggested to be regulated by a PKC-induced phosphorylation of claudin-4." (PMID 25409315, 2014). "Ovarian cancers of varying subtypes including mucinous, serous, undifferentiated, clear cell, and endometrioid carcinomas have been found to highly express claudin-3 and claudin-4 but normal ovarian surface epithelium does not." (PMID 23685873, 2013). "In particular, overexpression of claudin-3 or claudin-4 in ovarian cancer is based on the hypothesis that ovarian cancers originate from normal ovarian surface epithelial cells, which do not express claudin-3 or claudin-4." (PMID 24009024, 2013).
ovarian carcinoma (continued). "The analysis of a pilot panel of ovarian cancer cases (63 cancer patients and 50 controls) did indeed show that several ovarian cancer patients exhibited extremely high levels of claudin-4 in the plasma, while control individuals did not typically show elevated amounts of this protein." (PMID 19619303, 2009). "We reasoned that claudin-4’s reduction of genomic instability and slowing of mitosis may interfere with olaparib’s effects on OVCAR8, OVCA429, and OVCAR3 cells, which, despite classification discrepancies (OVCAR8 and OVCA429), are recognized as ovarian cancer cell lines." (PMID 39625235, 2025). "Aiming at identification of sEV proteins as diagnostic biomarkers for ovarian cancer, early studies have shown that some proteins from EVs such as claudin-4, TGF-β1 and MAGE3/6 may have certain diagnostic value in ovarian cancer, but no further demonstration was made in a larger population sample." (PMID 35954383, 2022). "Pairwise CLDN biomarker AUC comparisons (heatmap), across 12 tumor types (The Cancer Genome Atlas; TCGA data), showed that CLDN1 could readily distinguish colon from kidney, brain, lung, and ovary cancers, while both CLDN1 and CLDN4 (but not CLDN18) could distinguish brain from kidney cancer." (PMID 29050243, 2017).
breast carcinoma (67 papers, 2005 to 2026). "Claudin-4 (CLDN4) has been shown to be overexpressed in breast cancer and is associated with increased tumor aggressiveness and poor prognosis, particularly in TNBC." (PMID 40862714, 2025). "In breast cancer claudin-4 overexpression has been associated with progression, migration and worst prognosis, which is in concordance with our findings." (PMID 39687048, 2024). "The results showed that the CTC count and classification in breast cancer are associated with the expression of Claudin-4." (PMID 37465316, 2023). "The poor prognosis of gastric and breast cancer patients is associated with CLDN4 overexpression, in line with the poor prognostic value of CLDN7 in gastric cancer." (PMID 36672179, 2023). "Future studies should examine the diagnostic and prognostic values of CTCs and Claudin-4 in breast cancer patients." (PMID 37465316, 2023). "In breast cancer, on the other hand, C/EBPβ was associated with an increase in Claudin-4 (CLDN4) to promote cancer cell migration and invasion." (PMID 36675048, 2023). "In conclusion, CTC count and classification in breast cancer are associated with the expression of Claudin-4." (PMID 37465316, 2023). "Future large studies should attempt to investigate the diagnostic and prognostic value of CTCs and claudin-4 in breast cancer patients." (PMID 37465316, 2023). "Alternatively, relapse-free survival (RFS) was significantly shorter in high versus low CLDN2 or CLDN5 expression in breast cancer, with high CLDN4 expression also being associated with worse RFS." (PMID 36672179, 2023). "Especially, claudin-4, of which low expression is associated with breast cancer stem cell phenotype and poor prognosis, is significantly increased." (PMID 29190905, 2017). "Conversely, positive claudin-4 expression was associated with shorter disease-free survival and claudin-3 was related to longer disease-free survival in luminal types of breast cancer." (PMID 24009024, 2013). "Our observations are in agreement with a recent study in which claudin-4 expression was shown to be associated with high grade and poor prognosis in breast carcinoma." (PMID 19680458, 2010). "There are limited options available for treatment, but Clostridium perfringens Enterotoxin (CPE) and its interaction with Claudin-4, a possible diagnostic biomarker for breast cancer, can provide a molecular pathway basis for the development of treatment options for metastatic brain cancer." (PMID 36077843, 2022). "Moreover, we show that claudin-4 is associated with the formation of VM in human breast cancer cells." (PMID 25871476, 2015). "Loss of claudin 4 has already been reported in cases of lobular in situ carcinoma." (PMID 23657508, 2013). "Moreover, the present study also confirmed that the expression level of Claudin-4 was associated with lymph node metastasis and tumors ≥5 cm, suggesting that higher Claudin-4 expression may be associated with a poor prognosis in breast cancer." (PMID 37465316, 2023). "Low expression of Claudin-3, Claudin-4, and Claudin-7 (CLDN3, CLDN4, and CLDN7) is associated with 3 types of epithelial cancers: breast cancer (BRCA), STAD, and bladder cancer (BLCA)." (PMID 41082105, 2026). "High CLDN4 expression has been associated with lymph node metastasis and enhanced cancer stemness in breast cancer, suggesting CLDN4 contributes to maintaining an aggressive tumor microenvironment." (PMID 40687428, 2025). "For example, an anti-CLDN4 antibody increased Paclitaxel uptake and apoptosis in breast cancer models, enhancing chemosensitivity and reducing metastasis." (PMID 40508219, 2025). "On the other hand, the overexpression of claudin-4 has been reported to increase proliferation in breast cancer cells." (PMID 38867360, 2024). "On the other hand, the upregulation of CLDN-4 also plays a role in the malignancy of various cancers, including gastrointestinal cancers, breast cancers, and lung cancers." (PMID 38338691, 2024).
breast carcinoma (continued). "Targeting PVT1 exon 9 expression in a claudin-low breast cancer model via siRNA resulted in re-expression of CLDN4 and a significant reduction in migration." (PMID 38731853, 2024). "Another conclusion of our study is that the CLDN4 signaling LXRβ-dependently and independently regulates a range of gene expressions in breast cancer cells." (PMID 37059993, 2023). "Epigenetic silencing by DNA hypermethylation of other CLDNs have also been described, such as CLDN1 in podocytes and breast cancer and CLDN4 in bladder cancer." (PMID 36614243, 2023). "On the other hand, there are conflicting reports on the relationship between high CLDN4 expression and patient prognosis in the breast cancer." (PMID 37059993, 2023). "This was apparent because KO of the human CLDN4 gene led to a reduction in cell proliferation, migration, and invasion in two distinct breast cancer cell lines T47D and/or MCF-7." (PMID 37059993, 2023). "Our RNA sequencing analysis, using T47D and T47D:CLDN4–/– cells as well as MCF-7 cells and MCF-7:CLDN4–/– cells, first suggested a link between CLDN4 and LXRs signalings in breast cancer cells." (PMID 37059993, 2023). "Claudin-4 has been reported to regulate EMT through p21-activated kinase 4 (PAK4) expression in human breast cancer cells." (PMID 37465316, 2023). "Because both LXRβ and LXRβS432 were essential for the CLDN4-accelerated cell proliferation and tumor growth in breast cancer cells, the LXRβ- and LXRβS432-dependent CLDN4-controlling gene products would be critical to promote breast cancer progression." (PMID 37059993, 2023). "Taken collectively with the finding showing that LXRs greatly contribute to maintaining cholesterol homeostasis and fatty acid metabolism in normal and cancer cells, these results suggested that CLDN4 promotes breast cancer metabolism through LXRs." (PMID 37059993, 2023). "We first determined the CLDN4 expression in four representative human breast cancer cell lines, MCF-7, T47D, SKBR-3, and MDA-MB-231." (PMID 37059993, 2023). "To evaluate the involvement of CLDN4 in breast cancer progression, we subsequently established both T47D:CLDN4–/– and MCF-7:CLDN4–/– cell lines using CRISPR/Cas9-based genome editing." (PMID 37059993, 2023). "In summary, the present study highlighted that the CLDN4-based cell adhesion signaling accelerates breast cancer metabolism and advancement via LXRβ, especially through LXRβS432." (PMID 37059993, 2023). "This is reasonable because a series of our analyses disclosed that the CLDN4 signaling stimulates breast cancer progression through LXRβ." (PMID 37059993, 2023). "We uncovered that the CLDN4-adhesion signaling accelerated breast cancer metabolism and progression via LXRβ." (PMID 37059993, 2023). "Perhaps the most well-studied claudin in breast cancer is CLDN4, which has been found to be highly aberrant and has a role to define a subgroup of breast cancer." (PMID 38137355, 2023). "We next determined, by immunohistochemistry, the expression of both CLDN4 and LXRβ in breast cancer tissues resected from the 187 patients." (PMID 37059993, 2023). "CTC counts and Claudin-4 expression were independent predictors of poor prognosis in breast cancer patients." (PMID 37465316, 2023). "This study aimed to explore the relationship between peripheral blood CTCs and the expression of Claudin-4 in patients with breast cancer and their relationship with the survival and prognosis of breast cancer patients." (PMID 37465316, 2023). "On the other hand, although CLDN4 overexpression increased the migration of breast cancer cells, the invasiveness and metastatic potential of pancreatic cancer cells was shown to be decreased upon CLDN4 expression." (PMID 36672179, 2023). "Here, we show that aberrant CLDN4 signaling advances breast cancer metabolism and progression via liver X receptor β (LXRβ), a member of the nuclear receptor family." (PMID 37059993, 2023).